MCL1 (MCL1 apoptosis regulator, BCL2 family member)
Diseases named in the same sentence as MCL1 in open-access papers (continued):
Sharing a sentence is not in itself a finding about the gene and the disease.
melanoma (continued). "Our finding may be of importance for treatment of melanomas, as they demonstrate that silencing of Mcl-1 cannot only increase the cytotoxicity of the AdV-TRAIL in TRAIL-resistant melanoma cells but also in TRAIL-sensitive melanoma cells, even when Mcl-1 is expressed at a very low level." (PMID 34028599, 2021). "Moreover, our current study also includes in vitro data that tests a clinic-ready version of the MCL1 inhibitor, S64315 (MIK665), in combination with the FDA approved ABT-199, further justifying the use of this therapeutic option for patients with advanced melanoma." (PMID 32764384, 2020). "The results here suggest that the use of a combination of MCL-1 and BCL-2 inhibitors to induce NOXA and BIM is a promising treatment strategy for melanoma regardless of the mutation status of BRAF or NRAS, and it may overcome melanoma's resistance to current treatments." (PMID 27086916, 2017). "To test the hypothesis that expression of MCL-1, a known anti-apoptotic factor, can contribute to drug resistance, we targeted MCL-1 using a small molecule inhibitor (sabutoclax) in a variety of human melanomas, including BRAFV600E and non-BRAF stage III/stage IV metastatic melanoma cell lines." (PMID 27846237, 2016). "Therefore, EGb761 with or without in combination with targeting Mcl-1 may be a useful strategy in the treatment of melanoma." (PMID 25860257, 2015). "Furthermore, observations of increased Mcl-1 and Bcl-xL levels in thin primary melanomas as well as in metastatic malignant melanomas but not in benign nevi, suggest that up regulation of these proteins represents an early event associated with malignant transformation." (PMID 24223823, 2013). "Importantly, inhibition of RAS-Erk1/2 pathway in BRAFV600E mutant melanoma cell lines restores the LKB1-AMPK-mTOR pathway response to metabolic stress promoting apoptosis in coordination with the BH3-family proteins Bad and Bim and the Bcl-2 family member Mcl-1." (PMID 19274086, 2009). "Notably, the inhibition of the RAS pathway in BRAFV600E mutant melanoma cells recovered the complex formation and rescued the LKB1-AMPKα metabolic stress-induced response, increasing apoptosis in cooperation with the pro-apoptotic proteins Bad and Bim, and the down-regulation of Mcl-1." (PMID 19274086, 2009). "Treatment of resistant melanoma cells and their drug-naïve counterparts with 1 μM S63845 slightly increased MCL-1 protein levels without affecting MCL-1 mRNA levels." (PMID 37835493, 2023). "Toxicity data for MCL1 and BCL2 inhibition in humans has not been reported to date, however, early phase clinical trials assessing safety are underway in non-melanoma tumor types." (PMID 32764384, 2020). "In fact, forced BCL-XL expression does not determine a modulation of MCL-1 protein, and even downregulation of BCL-2 protein in our melanoma models." (PMID 29238043, 2017). "In melanoma, the NOXA/MCL-1/BCL-2 apoptotic node has emerged as a common vulnerable spot for targeting the MIC and non-MIC populations of melanoma." (PMID 27829238, 2016). "A MCL-1 specific inhibitor sabutoclax treatment is very effective not only in BRAFV600E-expressing lines, but also in non-BRAF melanomas that currently have no effective clinical options in the clinic." (PMID 27846237, 2016). "The increased sensitivity of melanoma to Obatoclax is consistent with the ability of Obatoclax, but not ABT-737, to inhibit Mcl-1." (PMID 24367627, 2013). "Finally, analysis of database of melanoma patients showed a significant correlation between the expression levels of HK2 and MCL1 (p = 2.3e-06, rho = 0.216) –but not BCL-2 (p = 1.98e-01, rho = 0.059) or BCL2L1 (p = 4.57e-01, rho = 0.034)." (PMID 41326406, 2025). "Inhibition of MCL-1 through miR-32 may be an effective anti-melanoma strategy, regardless of the status of NRAS, BRAF or PTEN, as MCL-1 inhibition exhibits synergistic effects with Vemurafenib." (PMID 32054078, 2020).
melanoma (continued). "As MCL-1 is not targeted by ABT-263, BH3-mimetic combinations with S63845 could provide further insight into whether MCL-1 was critical for melanoma cell survival." (PMID 31019203, 2019). "Here, we examined whether the potent MCL-1 inhibitor A-1210477, in combination with ABT-263, kills the MIC and non-MIC population of melanoma cell lines and relapsed patient samples." (PMID 30185782, 2018). "In the context of BRAF-mutant melanoma, the persistent activation of the MAPK signaling pathway not only augments cellular proliferation but also disrupts cell death signaling by upregulating the anti-apoptotic protein Mcl-1, ultimately resulting in resistance to BRAF inhibitors." (PMID 40331942, 2025). "Overexpression of Mcl-1 inhibited, albeit partially, reduction in cell viability in MM200, Sk-Mel-28, Mel-RMu, and IgR3 cells, suggesting that downregulation of Mcl-1 contributes to synergistic killing of BRAFV600E melanoma cells by the inhibitors irrespective of whether Bim is involved." (PMID 23744355, 2013).
multiple myeloma (220 papers, 2005 to 2026). "The MCL-1 gene is found on chromosome 1q21, along with the gene for the IL-6 receptor, and gains or amplifications of 1q21 seen in approximately 40% of multiple myeloma cases are associated with significantly shorter survival." (PMID 35127532, 2021). "Mitotic arrest leads to a rapid loss of MCL-1 and induction of apoptosis in myeloma cells, whereas MM cells with sustained expression of anti-apoptotic molecules (e.g., BCL-xL) or the capability to evade via mitotic slippage are less prone to mitotic blockers." (PMID 33308268, 2020). "Direct USP24 knockdown resulted in apoptosis of myeloma cells associated with a reduction in MCL1 levels." (PMID 32354135, 2020). "As expected, the loss-of-Mcl-1 observed with ABC294640 treatment sensitised myeloma cells to Venetoclax95." (PMID 30062053, 2018). "Flavopiridol and seliciclib induce apoptosis in myeloma cell lines and primary cells and this induced apoptosis is associated with Mcl-1 downregulation." (PMID 29163849, 2017). "The deubiquitinase USP9-X is overexpressed in lymphomas and multiple myeloma and stabilizes MCL-1 by removing K48-linked polyUb chains." (PMID 25340740, 2014). "In myeloma cells, Mcl-1-mediated regulation of apoptosis has been linked to its interaction with the proapoptotic BH3-only protein Bim." (PMID 21179037, 2011). "This activity, as well as flavopiridol's ability to reduce antiapoptotic protein MCL-1, has been implicated in the induction of apoptosis in multiple myeloma cell lines." (PMID 21092078, 2010). "With myeloma cells, others have also shown that the inhibition of protein geranylgeranylation causes the loss of Mcl-1." (PMID 19405951, 2009). "Noticeably, human myeloma often associates up-regulation of MCL1 and silencing of BNIP3." (PMID 36358756, 2022). "Myeloma cells in turn will cause an increase of MCL-1 expression and survival in MDSC." (PMID 33634031, 2020). "Previous studies identified miR-193b-3p as a top deregulated miRNA in myeloma cells and a direct regulator of the MCL1 transcript." (PMID 41244896, 2025). "For multiple myeloma (MM) samples, shown previously to be primarily MCL-1 dependent 29, all patients' highest score was the MCL-1 one, with patient 4 reaching a score of 61,58." (PMID 40365276, 2025). "In fact, over-expression of anti-apoptosis proteins Bcl-2 and Mcl-1 served as the hallmarks of leukaemia and myeloma; for this reason, the discovery of new drugs that can inhibit the expression of Bcl-2 and Mcl-1 is important in curing leukemia." (PMID 40141366, 2025). "For example, AML and myeloma models treated with the MCL1 inhibitor S63845 show increased expression of BCL2 and BCLXL, indicating a shift in apoptotic dependency." (PMID 41155156, 2025). "Previous studies have implicated miR-193b-5p in tumor progression in various cancers, and its variant miR-193b-3p has been identified as a key deregulated miRNA in myeloma cells, regulating MCL1 expression." (PMID 41244896, 2025). "BAK-deficient cells exhibit marked resistance to MCL1 inhibitors, while loss of BIM contributes to MCL1 resistance in lymphomas and myelomas." (PMID 41155156, 2025). "In Mcl-1-expressing myeloma cells, Bim distribution dictates Mcl-1 dependency or codependence with Bcl-2/Bcl-xL." (PMID 39411073, 2024). "For instance, it has been reported that high levels of BCL-2 expression were associated with increased sensitivity to ABT-199 in multiple myeloma (MM), but those cells were resistant when BCL-xL or MCL-1 were also expressed." (PMID 39497108, 2024). "The intricate interplay between anti-apoptotic (e.g., Bcl-2, Bcl-xL, Mcl-1) and pro-apoptotic (e.g., Bax, Bak, Bim, Puma, Bid, Noxa) proteins governs the apoptotic death of myeloma cells." (PMID 39411073, 2024). "This highlights the potential significance of Mcl-1 as a therapeutic target in managing myeloma characterized by dysregulated intrinsic apoptosis." (PMID 39411073, 2024).
multiple myeloma (continued). "In clinical studies, multiple myeloma (MM) patients with high MCL-1 level had shorter event free survival." (PMID 37601693, 2023). "A subset of multiple myeloma patients (40%) had amplification or gain of Mcl-1 gene (1q21), with significantly shorter progression-free survival and lower overall survival." (PMID 37601693, 2023). "S63845 was the first MCL-1 inhibitor reported to be effective in tumor models, binding human Mcl-1 at a Kd of 0.19 nM, and was shown to have broad therapeutic applicability in multiple myeloma, lymphoma, leukemia, and primary AML cell groups." (PMID 37259388, 2023). "What is more, targeting MCL1 also constrained the growth of myeloma in vivo, which is pivotal for maintaining survival of most myelomas, and it should be prioritized for targeting in the clinic." (PMID 37407915, 2023). "Upon stimulation of the JAK/STAT3 pathway, Mcl-1 expression was observed to be increased in myeloma cell lines, and in primary cells and cell lines once VEGF was available." (PMID 37046991, 2023). "Recently, the phase I clinical results of Mcl-1 inhibitor AMG-176 in 26 patients with relapsed multiple myeloma (MM) were disclosed." (PMID 36658493, 2023). "On the contrary, in large granular lymphocyte leukemia or multiple myeloma SPHK2 inhibition downregulates MCL-1 expression." (PMID 37020867, 2023). "AMG176, another Mcl-1 inhibitor, is being tested in participants with relapsed or refractory multiple myeloma, and in patients with relapsed or refractory acute myeloid leukemia (NCT02675452 clinical study phase I)." (PMID 37371761, 2023). "Bcl-2 and Mcl-1 proteins play a role in multiple myeloma (MM) cell survival, for which targeted inhibitors are being developed." (PMID 36672426, 2023). "MCL1 constrained the growth of myeloma in vivo, and has been verified to be involved in the development of Dex resistance in MM cell lines." (PMID 37407915, 2023). "These miRNAs were downregulated, and BCL2, BCL2L1, and MCL1 genes were upregulated in samples from AL amyloidosis patients compared with MM and HC samples." (PMID 36694297, 2023). "A series of studies indicated that MCL-1 is over-expressed in many cancer types (multiple myeloma, lymphomas, leukaemia) and therefore it is widely recognised as a druggable target." (PMID 35252355, 2022). "Noxa-induced Mcl-1 degradation has also been observed when Noxa was overexpressed in U266 myeloma cells and MEFs." (PMID 35207544, 2022). "In human myeloma cell lines (HMCLs), a synergism between of compounds individually inhibiting Bcl-2 and Mcl-1 has been confirmed, and the combination of these drugs overcomes Mcl-1 resistance in MM." (PMID 36387095, 2022). "Based on this, the researchers found that splicing inhibitors can sensitize multiple myeloma cells to venetoclax through its affection on MCL-1 transcripts, shifting cells from MCL-1-dependent to BCL-2-dependent." (PMID 36313732, 2022). "Treatment of the multiple myeloma cell with venetoclax showed an upregulation of MCL-1 but was mitigated with the combination of selinexor and venetoclax." (PMID 36261486, 2022). "Overexpression of Noxa has also been shown to disrupt Mcl-1/Bak complexes in multiple myeloma and B-cell lymphomas and in Jurkat cells." (PMID 35207544, 2022). "In myeloma, overexpressed MCL1 and BCL-XL leads to myeloma cell survival and resistance to venetoclax therapy." (PMID 35799216, 2022). "Multiple myeloma with Amp1q is particularly dependent on MCL1, which results in pronounced sensitivity to MCL1 inhibitors." (PMID 35912171, 2022). "Several other Bcl-2 inhibitors are in clinical development, as are inhibitors of Mcl-1, a Bcl-2-family oncoprotein that is perhaps more critical for myeloma cell survival than Bcl-2." (PMID 35884390, 2022). "Inflammatory cytokines such as IL-6, derived from bone marrow (BM), mediate BCL2, BCLXL, and MCL1 expression in MM, forming complex network interactions between the marrow stroma and myeloma cells." (PMID 35982976, 2022).
multiple myeloma (continued). "Specifically, most myeloma cell lines (80%) are dependent on the anti-apoptotic MCL1 protein or both MCL1 and BCLXL, being the most dominant pro-survival protein in MM." (PMID 35982976, 2022). "As for Mcl-1, its important roles have been reported in hematopoietic cancer cells of different types, such as multiple myeloma (MM), diffuse large B-cell lymphoma (DLBCL), mantle cell lymphoma (MCL) as well as in non-Hodgkin and T-cell lymphomas." (PMID 36293331, 2022). "USP9X can bind and remove polyubiquitin chains from MCL1 targeted for degradation, and its expression correlates with MCL1 overexpression in follicular lymphoma, diffuse large B-cell lymphoma, and multiple myeloma." (PMID 36551253, 2022). "Here we show that the clonal plasma cells in AL amyloidosis are highly primed to undergo apoptosis and dependent on pro-survival proteins MCL-1 and BCL-2." (PMID 36184661, 2022). "Most MM cell lines are dependent on MCL-1 for survival, and targeting MCL-1 induces apoptosis in approximately 70% of myeloma cell lines." (PMID 33883020, 2021). "Preclinical data has also demonstrated that myeloma cell lines harboring 1q21 amplifications are particularly sensitive to Mcl-1 inhibition." (PMID 35127532, 2021). "On the other hand, high expression levels of miR-137 have been observed in dexamethasone-treated multiple myeloma cells by targeting MCL-1 and MITF genes, thus inhibiting cancer cell proliferation and inducing apoptosis." (PMID 33670982, 2021). "Co-expression of BCL2 and MCL1 has been reported in NHLs and MCL1 dependency is also seen in acute myelogenous leukemia and multiple myeloma." (PMID 33670870, 2021). "Although, Mcl-1 inhibitors have good anti-myeloma activity as a monotherapy in hematological cancer models, most development strategies are focused on combination, which can increase the potential of these molecules." (PMID 34349655, 2021). "Although both BCL‐2 and MCL‐1 are necessary for MM survival, most myelomas are dependent on MCL‐1 such that BCL‐2 inhibition alone only yields significant response in a minority of cases." (PMID 35846088, 2021). "MCL-1 inhibitors are in clinical development with a focus on haematopoietic cancers including multiple myeloma and acute myeloid leukemia." (PMID 33785871, 2021). "MicroRNAs miR-193b-3p and miR-21-5p emerged among the top deregulated miRNAs in myeloma cells when directly co-cultured with pMSCs, and we show their contribution to changes in MCL-1 and BCL-2 protein expression and in the activity of S63845 and venetoclax." (PMID 33806619, 2021). "Several Mcl-1 inhibitors are being tested in multiple myeloma in various preclinical and early clinical stages." (PMID 35127532, 2021). "We show that co‐operative targeting of BCL‐2 and MCL‐1 with venetoclax and S63845, induces a synergistic apoptotic response, in human myeloma cell lines (HMCL) and primary samples." (PMID 35846088, 2021). "The emodin-stimulated apoptosis was almost abolished in myeloma cells overexpressing Mcl-1, close to the degree in parental cells untreated with emodin, proposing the significance of Mcl-1 in the stimulation of apoptosis by emodin." (PMID 34073059, 2021). "Mcl-1 is an important antiapoptotic gene, promoting cell survival in various hematological malignancies, including multiple myeloma (MM), acute myeloid leukemia (AML), and NHL." (PMID 34833935, 2021). "For example, MCL-1 inhibition led to significant induction of apoptosis in primary human multiple myeloma samples and amplification of 1q21 (containing MCL-1), which occurs in around 40% of newly diagnosed disease, correlated with sensitivity." (PMID 35008216, 2021). "By myeloid cell leukemia 1 (Mcl-1) elimination, cytotoxicity in human myeloma cells was remarkably stimulated by emodin." (PMID 34073059, 2021). "The anti‐apoptotic proteins B‐cell lymphoma‐2 (BCL‐2) and myeloid cell leukaemia‐1 (MCL‐1), are necessary for MM survival, although most myelomas are more dependent on MCL‐1." (PMID 35846088, 2021).